ATR (ATR checkpoint kinase)
Diseases named in the same sentence as ATR in open-access papers (continued):
Sharing a sentence is not in itself a finding about the gene and the disease.
prostate carcinoma (continued). "For example, phosphorylation of RRM1 regulates DNA replication and ATR inhibition vulnerability, while RRM2 drives aggressive prostate cancer and hepatocellular carcinoma, suggesting their importance for targeted therapies 38,39." (PMID 37737478, 2023). "Again, in line with data reported here, it has been recently shown that in cellular models of castration-resistant prostate cancer, MET inhibition enhances the efficacy of PARPi by suppressing the ATM/ATR and PI3K/AKT pathways." (PMID 35628590, 2022). "A recent report also showed that ATR inhibits CDK1-SPOP signaling and thus enhances anti-PD-L1 cytotoxicity in prostate cancer." (PMID 36090896, 2022). "This study identified the ATR inhibitor as the most synergistic inhibitor for both radiation qualities, supporting further pre-clinical evaluation of DDR inhibitors in combination with 223Ra for the treatment of prostate cancer." (PMID 38672592, 2024). "CNVs at this site may activate its nearby oncogenes such as ATR, BCL6 and PI3K family, leading to aggressive cancer hallmarks in prostate cancer." (PMID 38279874, 2024). "mRNA expression of ATR in tumor tissue was increased compared with matched non-malignant tissue in liver, lung, uterus, and prostate cancers, but not in breast and kidney cancers." (PMID 32111912, 2020). "In prostate cancer, besides PARP inhibition, the targeting of DDR molecules such as ATM/ATR might be explored also in combination with chemotherapy, immunotherapy, and AR-targeted agents." (PMID 31242618, 2019). "Importantly, the HRR abnormalities are observed in 31% of advanced prostate cancers and include: BRCA2 (9.8%), CDK12 (5.6%), ATM (5.2%), CHEK2 (1.8%), BRCA1 (1.4%) FANCA (1.3%), and ATR (1.1%)." (PMID 31366128, 2019). "The fact that androgen treatment alone can induce TMPRSS2: ERG fusion in the prostate cancer, LNCaP, cell line suggests that these cells may contain a detective ATM/ATR DNA damage checkpoint." (PMID 23272087, 2012). "Intriguingly, unlike the non-malignant prostate epithelial cells, the ATM/ATR DNA damage checkpoint appears to be defective in prostate cancer cells, since androgen treatment only induced a partial activation of the DNA damage response." (PMID 23272087, 2012). "A study using prostate cancer cell lines agreed that ATM loss may not respond to PARPis, but they did respond well to an ATR inhibitor." (PMID 33233320, 2020). "Moreover, ATR inactivation has been proposed to be synthetic lethal with ATM inactivation because of the overlapping substrates and functions of ATR and ATM, and because ATM appears inactivated in a significant proportion of cancers (10–16% of colorectal, gastric, lung and prostate cancers)." (PMID 34572827, 2021). "ATR inhibition can also inflame the TME in the absence of DNA-damaging agents, such as through the direct activation of a CDK1 axis, leading to SPOP-dependent PDL1 degradation in prostate cancer cell lines." (PMID 38473997, 2024).
Fanconi anemia (54 papers, 2004 to 2026). Fanconi anemia (FA) is a hereditary DNA repair disorder characterized by progressive pancytopenia with bone marrow failure, variable congenital malformations and predisposition to develop hematological or solid tumors. "The Cancer Genome Atlas (TCGA) analysis reported that HGSC tumors are characterized by mutations in PTEN (7%), RAD51C (3%), ATM/ATR (2%) and Fanconi anemia genes (5%)." (PMID 36531003, 2022). "Although they mainly affect the BRCA1 and BRCA2 genes, they have been detected in other genes such as RAD51C hypermethylation (RAD51 paralog C), ATM (ataxia telangiectasia mutated serine-protein kinase gene), or ATR mutations, and mutations of the HR interacting Fanconi anemia gene." (PMID 34638899, 2021). "Although breast tumor tissue from the affected carriers was not available for LOH or HRD assessment, prior studies suggest that impaired ATRIP function may disrupt ATR-mediated checkpoint and the Fanconi anemia repair pathway, both of which are closely linked to HRR." (PMID 41440239, 2025). "Notably, patients with ATM/ATR pathogenic genetic alterations were likely to be accompanied by mutations in Fanconi anemia (FA) and homologous recombination (HR) pathways, which were confirmed using both the study (P < 0.001) and validation (P < 0.001) cohorts." (PMID 38041093, 2023). "Transcriptional profiling during bleomycin challenge identified 18 DDR genes with relatively higher expression in PET-exposed cells compared to passage-matched controls, encompassing HR, BER, ATM/ATR signaling, the Fanconi anemia pathway, and apoptosis." (PMID 42278555, 2026). "ICL traversal also depends on ATR and the Fanconi anemia pathway and involves, among other proteins, FANCM, FANCD2 and PRIMPOL." (PMID 39766854, 2024). "Meanwhile, studies have shown that HPV activates ATM and ATR pathways and fanconi anemia pathways, which are critical pathways in DNA damage repair network." (PMID 35309134, 2022). "In our work, transcriptomic studies revealed that functions involved in DNA damage such as those classified as ATM, ATR, Fanconi Anemia, and BARD1 pathways are clearly dysregulated in breast tumors, particularly in the basal-like and HER2 subtype." (PMID 33925616, 2021). "ATR orchestrates cell responses to replication stress, including activation of the Fanconi anaemia (FA) pathway of ICL recognition and repair." (PMID 31273933, 2019). "Activated ATR allowed the recruitment of the Fanconi anemia DNA cross-link repair pathway, evidenced by the activation of FANCD2 and its recruitment in subnuclear foci together with p-H2AX." (PMID 29559578, 2018). "Next, we verified that activation of the Fanconi anemia pathway upon infection with DH10B pBACpks was mediated by an ATR-dependent replication stress response." (PMID 29559578, 2018). "There are numerous genes involved in the DDR pathway, and several studies suggest that platinum therapy may benefit patients with mutations in genes such as ATM and ATR, those within the MRN complex (e.g., RAD50), and Fanconi anemia core genes." (PMID 39860372, 2025). "Additionally, significant roles are played by PALB2, ATM, ATR, CHEK1, CHEK2, RAD51, and genes linked to Fanconi anaemia." (PMID 40069561, 2025). "In addition, the top two enriched KEGG pathways were: 1) the Fanconi Anaemia pathway (represented by ATR, BRIP1, ERCC4, FANCC and POLH) and the FoxO signalling pathway (represented by CREBBP, NLK, PRKAA2, PRKAB1, PTEN and STK11)." (PMID 35768547, 2022).
Fanconi anemia (continued). "Other defects in homologous recombination repair genes, such as EMSY, RAD51, ATM, ATR, Fanconi anemia, BARD1, BRIP1, PALB2, RB1, NF1, CDKN2A, and the suppression of BRCA1 transcriptional activation through gene methylation, are associated with homologous recombination deficiency (HRD)." (PMID 32679669, 2020). "Indeed, this NEK2 inhibition is dependent of ATM, a protein that, along with ATR, are master controllers of cell cycle and DNA repair, the main pathway deregulated in Fanconi Anemia." (PMID 31266445, 2019). "The gene panel used for the analyses of the DNA of 41 patients by massive sequencing detected the presence of numerous variants in genes coding for proteins involved in DNA repair such as ATM, ATR, BRCA1, BRCA2 and several genes of the FANC complex, mutated in Fanconi Anemia." (PMID 30995915, 2019). "Thus, induction of early genomic DNA ICLs by colibactins resulted in replication stress and activation of the ATR and Fanconi anemia repair pathways." (PMID 29559578, 2018). "Replication stress is known to induce DNA damage due to the stalled or collapsed forks, which then activates ATM/ATR-mediated cell cycle checkpoint responses to promote fork stability and restart thorough Rad18 and Fanconi anemia (FA) DNA repair pathways (monoubiquitinated FANCD2)." (PMID 25742788, 2015). "In addition to BRCA1/2 deficiency, the amplification of EMSY and deficiencies in PTEN, Fanconi Anemia genes, RAD genes and DNA repair genes involved in HR (including ATM, ATR and CHEK1/2) have also been identified to cause HR defects in human cancer." (PMID 25437005, 2014). "The recovery of ATR protein function in PSCs may also be beneficial to obtaining the ATR-SS iPSC clones, which will advance models for other diseases with defective DNA repair pathways such as Fanconi anemia, since current reprogramming efficiency is extremely low." (PMID 30846821, 2019). "Interestingly, the fanconi anemia pathway interacts with the ATR signaling pathway." (PMID 25893139, 2013). "ATR phosphorylates these sites to permit chromatin loading of the FANCD2/FANCI complex and activation of the Fanconi anemia pathway." (PMID 37392383, 2023). "HRR alterations involve Fanconi anemia genes (PALB2, FANCA, FANCL, FANCI, FANCC), core RAD genes (RAD50, RAD51, RAD51B, RAD51C) as well as DNA damage response genes (ATM, ATR, CHEK1, CHEK2)." (PMID 36531003, 2022). "In GSEA analysis, several pathways were significantly enriched corresponding to the E2F2 high expression phenotype, including ATR pathway, ATM signalling pathway, mismatch repair, base excision repair, homologous recomibination and Fanconi Anemia pathway." (PMID 35069909, 2022). "Genes included in different pathways, such as ATM/ATR, BARD1, and Fanconi Anemia, which are involved in the DNA damage response, were selected and confirmed using molecular alterations data contained at cBioportal." (PMID 33925616, 2021). "For example, a module composed of a FoxM1 transcription factor network, an E2F transcription factor network, Aurora B kinase signaling, ATR signaling, PLK1 signaling, and members of the Fanconi anemia DNA damage response pathway was densely connected." (PMID 29988723, 2018). "The Fanconi anemia (FA) pathway is a part of the DNA damage response and mediates cross talk between the ATM and ATR pathways." (PMID 28196964, 2017). "The Fanconi anemia (FA) pathway cross talks with the ATM and ATR pathways in cell cycle control and the repair of DNA interstrand cross-links." (PMID 28196964, 2017). "In fact, loss of most genes involved in DNA damage checkpoints or DNA damage repair, such as ATM, ATR, BRCA1, BRCA2, Fanconi anemia genes, lead to increased sensitivity to genotoxic agents." (PMID 15494723, 2004).
Fanconi anemia (continued). "Among these 14 pathways, four major pathways were enriched: SNARE interactions involved in the vesicular transport (BET1 and STX6), leishmaniasis (FCGR1A, CYBB, and FOS), hematopoietic cell lineages (FCGR1A, ITGA3, MME, and CD5) and Fanconi anemia pathway (SLX4, ATR, and TELO2)." (PMID 37601105, 2023). "Several signal pathways were significantly enriched in high E2F2 expression group, including ATR pathway, ATM signalling pathway, mismatch repair, base excision repair, homologous recomibination and Fanconi Anemia pathway." (PMID 35069909, 2022). "GSEA disclosed that E2F2 was probably involved in several pathways, including ATR pathway, ATM signalling pathway, mismatch repair, base excision repair, homologous recomibination, Fanconi Anemia pathway, multicancer invasiveness signature, and cancer stem cells." (PMID 35069909, 2022). "Relevant to the adaptation of TRD to arid conditions, ten selected genes (including SLX4, FANCF, FANCG, FANCI, ATR, and POLH) were related to the fanconi anemia pathway (bta03460, p < 0.01) involved in DNA repair, DNA replication fork stability, and other cellular processes." (PMID 33072165, 2020). "Besides, some other core components of HR such as RAD51 recombinase (RAD51), ATM serine/threonine kinase (ATM), ATR serine/threonine kinase (ATR), partner and localizer of BRCA2 (PALB2), and Fanconi anemia gene family are determinants of intact HR as well." (PMID 31737426, 2019). "The central complex in this pathway is formed by the Fanconi anemia complementation group D2 (Fancd2), a core component of the Fanconi anemia complex, and FAI (FANCI) proteins forming the FANC1-FANCD2 (ID) complex that are phosphorylated by ATR (ataxia telangiectasia and Rad3-related)." (PMID 29234487, 2017). "Moreover, E2F2 is possibly involved in CRC tumorigenesis and development via modulating ATR pathway, ATM signalling pathway, mismatch repair, base excision repair, homologous recomibination, Fanconi Anemia pathway, multicancer invasiveness signature, cancer stem cells and immune infiltrating cells." (PMID 35069909, 2022).
pancreatic cancer (49 papers, 2009 to 2025). "Parallel studies in human pancreatic cancer cells showed that the loss of APE2 significantly impairs ATR–Chk1 activation across diverse genotoxic stresses." (PMID 41446759, 2025). "In cells harboring ATM mutations, PARPi or ATR inhibitors enhanced the apoptosis rate of pancreatic cancer and subsequently increased synthetic lethality." (PMID 38184614, 2024). "Synthetic lethal interactions between ATM and ATR have also been observed, with ATM-deficient pancreatic cancer cell lines showing growth inhibition to ATR inhibitors." (PMID 31963441, 2020). "An ATR (M211T; rs2227928) variant found in the genome has been associated with a poorer response to gemcitabine and radiation therapy in pancreatic cancer." (PMID 22938532, 2012). "Vice versa, as POLA1 mutations occur in about 7 % of colorectal and pancreatic cancer samples, we additionally used four different ATR and CHK1 inhibitors to assess the chemical inducibility of synthetic lethality in various POLA1-depleted colon and pancreatic cancer cell lines." (PMID 39128273, 2024). "APE2’s exonuclease activity, enhanced by PCNA, creates longer ssDNA gaps (∼18–26 nt), which allow robust RPA coating and full ATR checkpoint assembly as shown in pancreatic cancer cells." (PMID 41446759, 2025). "Berzosertib (VE-822, 19), a highly selective ATR inhibitor, has demonstrated significant efficacy in suppressing pancreatic tumour progression while exhibiting minimal off-target toxicity in normal tissues." (PMID 40256842, 2025). "For instance, in mouse models of pancreatic tumours, the co-expression of mutated KRAS and catalytically active ATR mutations accelerate tumorigenesis and suppress immune responses." (PMID 40256842, 2025). "ATR stimulating CHK1 activation protects oncogenic K-Ras-expressing pancreatic cancer cells from DNA damage induced by the irradiation mimic neocarzinostatin, potentially through interference with G2 arrest and successful DSB repair." (PMID 36313934, 2023). "In PSN-1, MiaPaCa-2 and primary PancM pancreatic cancer cells, VE-821, as the first highly selective and potent ATR inhibitor, increased sensitivity to radiation doses of 2, 4 and 6 Gy in vitro." (PMID 36313934, 2023). "Celastrol prevented APE2’s ssDNA binding and 3'-5' exonuclease activity, and attenuated ATR activation in response to DNA damage in pancreatic cancer cells." (PMID 36755963, 2023). "Due to the role of CHK1 in G2 arrest and, consequently, HR repair of DSB, CHK1 and ATR have been described to be targets in combination with DNA damage-inducing agents as treatment approaches for pancreatic cancers." (PMID 36313934, 2023). "As discussed in a previous section, besides BRCA1 and BRCA2 mutations, mutations in PALB2, ATM, ATR, BRIP1, BARD1 and CDK12 are observed in low frequencies in pancreatic cancers." (PMID 36975505, 2023). "Overall, we have demonstrated the important function of APE2 in the ATR-Chk1 DDR pathway in pancreatic cancer cells, which can be targeted for future combination or synthetic lethality therapies for cancers." (PMID 34796173, 2021). "Our data here support the role of Celastrol in the suppression of the ATR-Chk1 DDR pathway under stress conditions via inhibiting APE2 in human pancreatic cancer cells." (PMID 34796173, 2021). "An ongoing trial assessing an oral ATR inhibitor in combination with olaparib for advanced solid tumors (including ATM mutant pancreatic cancer) will be informative (ClinicalTrials.gov Identifier: NCT03682289)." (PMID 34572943, 2021).